CD4 (CD4 molecule)
Diseases named in the same sentence as CD4 in open-access papers (continued):
Sharing a sentence is not in itself a finding about the gene and the disease.
tumor (continued). "Treg cells, defined as CD4+CD25+Foxp3+ T cells, are a subpopulation of lymphocytes that are crucial in maintaining tolerance to self-antigens and innocuous foreign antigens under physiological conditions, but can also be co-opted by tumor cells to avoid the host immune response." (PMID 36230505, 2022). "Similarly, only large numbers of CD4 T cells were present, but tumor growth was not inhibited without large numbers of CD8 T cells." (PMID 36232485, 2022). "In the analysis of tumor tissue cells, the tendencies were more obvious: the CD4+/CD8+ ratio in the metastasis group and nonmetastasis group was 1.66 ± 0.38 and 1.18 ± 0.29, respectively (P < 0.001), and the CCR5+/CD4+ ratio was 0.46 ± 0.08 and 0.18 ± 0.04, respectively (P < 0.001)." (PMID 36033472, 2022). "Hence, CD4-IL-21/CD8-CX3CR1 pathway is operational during tumorigenesis and could be used therapeutically to enhance CD8+ T cells killer functions over tumor progression." (PMID 35008422, 2022). "The relative proportions of tumour CD4+ and CD8+ T cells were not modified by N6L treatment." (PMID 36077801, 2022). "However, earlier studies in animal models have shown that CD4+ T cells, which recognize antigen via HLA class II (HLA-II) molecules rather than HLA-I, can also directly kill tumor cells." (PMID 35831288, 2022). "In addition, we found that 10 mg/kg DIM treatment could significantly elevate the percentages of CD4+ and CD8+ T cells in blood, spleen and tumor compared with the vehicle group." (PMID 35773674, 2022). "Analysis of the proportion of CD4+ T, CD8+ T, and central memory T cells (CD44+ CD62L+) showed that SPNI-mediated photodynamic immunotherapy can be used as a vaccine for cancer to stimulate strong anti-tumor T cell immunity, which helps to inhibit local and surrounding tumor growth." (PMID 35832074, 2022). "CD3, CD4, CD5, and CD8 may contribute to PD-1-mediated tumour control." (PMID 36514573, 2022). "Furthermore, a strong positive correlation (r = 0.783, p < 0.0001) was observed between levels of FoxP3+ Tregs and CD4+LAG-3+ T cells in tumor tissues but not in PBMCs and NILs." (PMID 35455287, 2022). "CD4+T can promote the activation of CD8+CTLs, boost the effector and memory functions of CTLs, and reduce the immunosuppression of CTLs, which helps T cells amplify their response to tumor-associated antigens without generating an autoimmune response." (PMID 36051923, 2022). "Furthermore, the tumor infiltrations of neutrophils, dendritic cells, CD4+ T cells, and B cells did not significantly impact the survival outcome of ccRCC patients." (PMID 35456435, 2022). "In the CT26 mouse model, anlo could increase the number of CD4+ cells but not CD8+ cells in the CT26 tumor-bearing mouse model." (PMID 36238642, 2022). "On the other hand, CD4+ regulatory T cells (Tregs), which are characterized by their immune-suppressive activity and by the expression of the transcription factor forkhead box P3 (FOXP3), play a pivotal role in promoting tumor progression by suppressing effective antitumor immunity." (PMID 35267528, 2022). "Besides CD4-positive TEMRA cells, GPR56 was also previously identified within a core transcriptome signature of human memory CX3CR1-positive CD8 T cells, and within a gene signature of CD39 and CD103 double-positive tumor-reactive CD8 T cells." (PMID 35804934, 2022). "The ratio of CD4+/CD8+ T cells and the levels of their characteristically secreted cytokines, IFN-γ and IL-2, were induced to decrease by the tumor cells, while these immunosuppressive issues could be reversed via inhibiting the activation of STAT3 pathway by rosmarinic acid." (PMID 36615387, 2022). "In B16–F10 cells, CPhGs increased the level of CD4+ and CD8+ T cells and induce the mitochondrial pathway of apoptosis, which suggests that CPhGs may regulate the immunoregulatory effects to inhibit the growth of tumor." (PMID 36532852, 2022).
tumor (continued). "Although the transferred CD45.1+ WT CD4+ T cells acquired Th2 phenotype in PyMtOvatg Csf2rbKO Csf2rb2KO tumors, they failed to suppress tumor growth, extend animals’ survival, or promote tumor differentiation compared with TslprKO CD4+ T cells in Tslptg TslprKO mice." (PMID 35657353, 2022). "Since p40 mAb upregulated human CD4+IFNγ+ and CD8+IFNγ+ T cells in the spleen of PDX mice, next we investigated whether p40 mAb treatment was capable of mounting these immune responses in vivo in tumor tissues." (PMID 35053375, 2022). "However, the number of Tregs (CD4+ CD25+ FoxP3+) were significantly lower in the tumors of LECMHC-II−/− mice but not different in tumor-draining LNs or spleens." (PMID 36362253, 2022). "In most cancers, Th2 CD4+ T cells have been shown to support tumor growth and progression, which could form an immunosuppressive milieu to hamper the activation of CD8+ T cells for eradicating the tumor cells." (PMID 35277569, 2022). "Research will be necessary to determine which type of cyTreg, whether CD4+ pTreg or tTreg, would be more effective killers in the TME, and to determine what engages the cytolytic potential versus other suppressive mechanisms against tumor cells." (PMID 35493508, 2022). "Based on the EPIC algorithm, CCNA2 and CDK2 expression levels in SARC were negatively correlated with the infiltration level of CD4+ T cells (cor = −0.194, P = 2.62e−03), implying that our dimers also could target CCNA2 and CDK2 to affect the tumor immunity in MG-63 cells." (PMID 36325324, 2022). "Furthermore, expression of PD-1 and 4-1BB on CD4+ and CD8+ T cells and PD-L1 on DCs has been reported in the tumor-draining lymph nodes from patients, suggesting that GEN1046 may further boost tumor-specific T-cell activation in tumor-draining lymph nodes." (PMID 35176764, 2022). "Given the role of CD4+ T helper cells, B cells, and other MHCII+ immune cells in antigen presentation, these results could indicate enhanced antigen presentation in compartmentalized tumor regions as compared to mixed regions." (PMID 35217711, 2022). "Furthermore, E7 RNA-LPX vaccinated mice displayed a higher fraction of intratumoral CD4+, CD8+, NK cells and E7-specific CD8+T cells in the tumor as well as in spleens and lymph nodes of treated mice when compared to LRT with control RNA-LPX, which only mildly modulated these cell populations." (PMID 34971406, 2022). "In addition, both CD4+ and CD8+ T cells were evident amongst the Kaede Red+ population within the dLN, but also the cLN and spleen, demonstrating that some immune cells egress the tumor and circulate through peripheral lymphoid tissues." (PMID 35472220, 2022). "The reduction of tumor hypoxia in E7 RNA-LPX/LRT-treated mice was furthermore was associated with markedly increased proliferation of CD8+ tumor infiltrated lymphocytes (TIL) five days after LRT, as shown by the higher incorporation of the base analog BrdU in CD8+ TIL but not in CD4+ TIL." (PMID 34971406, 2022). "Furthermore, both BC-MSCs and BC-MSCs-EVs could inhibit production of IFN-γ by CD4+ and CD8+ T cells, thus thwarting the anti-tumor immune response." (PMID 35842634, 2022). "Adoptive transferring of activin A-treated lung tumor-infiltrating CD4+ T cells into CD4 (-/-)-tumor-bearing mice could suppress tumor progression without CD4+ T cell exhaustion.." (PMID 35774793, 2022). "Altogether, the impairment of HCMV-specific CD4+ and CD8+ T cells and NK cells function, parallel to the enhancement of the activity of Treg, CD28− T cells, and Th17 cells could favor both viral spread and tumor development." (PMID 35458542, 2022). "However, there was a significant increase in ICOS expression on non-Treg CD4+ T cells in the tumor (62.16% vs. 34.04%, p = 0.004, n = 5/group)." (PMID 36056093, 2022).
tumor (continued). "Another major challenge for the selection of the best targets for a CD4+ T-cell-based immunotherapy is to identify which of the immunogenic neo-epitopes are generated by the MHC class II processing machinery and displayed by the tumor cells for T-cell recognition." (PMID 35655709, 2022). "The CD4+ T clones were slightly expanded in tumor tissues (T), nearest non-cancer tissues (N), and distal normal tissues (D), reflecting the local activation and expansion of intra-tissues CD4+ T clones happened during neoadjuvant pembrolizumab and chemotherapy." (PMID 35831283, 2022). "For example, macrophages and memory CD4 and B cells were enriched in the entire tumor of P1 but not in individual regions, suggesting a high variability in immune cell type enrichment among tumor regions." (PMID 36362107, 2022). "Studies have shown that dendritic cells, M1 macrophages, TH1 CD4+ T cells, cytotoxic CD8+ T cells and NK cells protect against tumor growth, while M2 macrophages, myeloid-derived suppressor cells (MDSCs), neutrophils, and certain regulatory T cells (Tregs) can promote tumor growth." (PMID 36389815, 2022). "Because BNL tumor does not express MHC-II, the authors suggested that tumor killing in vitro likely occurred through the presentation of tumor antigens to DC/BNL-primed CD4+ CTLs leading to perforin-mediated MHC-independent killing of nearby MHC-II-negative tumor cells." (PMID 36159781, 2022). "Here we find that in human and mouse tumour tissue, PI3Kδ inhibition leads to substantial changes in the cell composition of the TME by reducing the number of Treg cells and activating intratumoural CD4+ and CD8+ T cells, which clonally expand and display heightened cytotoxic and cytolytic features." (PMID 35508656, 2022). "However, we detected neither significant changes in tumor-infiltrating CD8+ cytotoxic T cells or CD4+ Th cells nor differences in natural killer cells, macrophages, or myeloid-derived suppressor cells between WT and GLSECKO in both E0771 and MMTV-PyMT tumors." (PMID 36381236, 2022). "In addition, IHC staining of CD4 and CD8 was performed in tumor xenografts." (PMID 36536402, 2022). "Others have proposed that, even though treatment with anti-PD-1/PD-L1 and anti-CTLA-4 antibodies would usually expand anti-tumor CD8 + and CD4 + T cells, such treatment might, upon certain circumstances, increase the population of PD-1 + T regs producing an effect of immunosuppression." (PMID 35922755, 2022). "CD4+ T cell depletion in mice immunized with pBARF1 did not affect tumor control." (PMID 35071745, 2022). "Based on evidence from a publicly available database of melanoma tumor antigen-specific TCR sequences, a previous study determined TCR clonotype clusters and found a marked enrichment of convergent TCR clusters in the CD39+PD-1+ subpopulation of CD4+ and CD8+ TILs." (PMID 36451828, 2022). "However, the tumor volume and survival rates of Alb-IFNβ and E7 -treated tumor-bearing mice did not significantly change by depletion of CD4 +T cells." (PMID 35459734, 2022). "Intriguingly, recently activated CD4+ T cells co-localized with pre-exhausted CD8+ T cells in tumor areas and could not be detected through their presence alone, indicating a possible target for precise pathology assessments." (PMID 35440049, 2022). "Similarly to tumor-infiltrating T cells, splenic CD8+ and CD4+ T cells in mice treated with the combination of AHCC® and DICB had increased expression of Ki-67 and CTLA-4 while granzyme B expression in splenic CD8+ and CD4+ T cells were barely detected by flow cytometry." (PMID 35514996, 2022). "Additionally, it was found that genetic ablation of CD73, a surface ecto-5’-nucleotidase that converts adenosine monophosphate (AMP) to immunosuppressive adenosine, lowers GM-CSF in the tumor microenvironment thereby preventing MDSC development and improving CD4+ and CD8+ effector T cell responses." (PMID 35865534, 2022).
tumor (continued). "In vitro, PD-1 blockade potentiates activation of CD4 tumor-infiltrating lymphocytes, as manifested by elevated CD154 level and cytokine generation, contributing to the improvement of dendritic cell maturation and ultimately enhanced proliferation of tumor-specific CD8 T cells." (PMID 35485300, 2022). "Further analysis revealed that CD4+ helper T cells (CD45+CD3+CD4+) were not significantly different between these two groups, and the percentage of tumor-infiltrated CD8+ CTLs (CD45+CD3+CD8+) was significantly higher in the Stk10−/− mice compared to that in WT mice." (PMID 36421382, 2022). "Overall, CD4+, CD8+, CD19+, and CD11b+Ly6G+ subsets had fewer LAIR-1+ cells, while NK cells, NKT cells, CD11b+Ly6Chi cells, and CD11b+F4/80hi macrophages had higher percentages of LAIR-1+ cells, particularly at the tumor site compared with the spleen and blood." (PMID 35230974, 2022). "Interestingly, we observed an increased frequency of DCs in the tumor microenvironment of IL-6-/- mice, but not CD4+ T cells or CD8+ T cells at the time point assessed." (PMID 36405719, 2022). "Analysis of the xCell gene sets showed highly significant enrichment of signatures associated with B cells and T cells (CD4 + and CD8 + ) in node-negative tumours with a high LN yield patient suggesting a broad activation of the adaptive immune response in these tumours." (PMID 35043009, 2022). "Tumor draining lymph nodes (TdLN) and tumor-infiltrating lymphocytes (TILs) were harvested from tumor-bearing mice (or inguinal lymph nodes from control naive animals) at day 20 post-tumor injection, and the expression of CD45, CD4, Foxp3, CD49b, and IL-10 was analyzed by flow cytometry." (PMID 35860556, 2022). "Importantly, both CD4+ T cells and CD8+ T cells contribute to the anti-tumor immune response." (PMID 35251028, 2022). "Contrarily, inflamed tumors exhibit an immune-inflamed phenotype, which is characterized by the presence of both CD4- and CD8-expressing T cells in the tumor parenchyma, usually accompanied by myeloid cells and monocyte cells, and the immune cells are located near the tumor cells." (PMID 36212436, 2022). "Interestingly, we discovered that both pro-tumor (myeloid-derived suppressor cells (MDSCs), regulatory T cells (Tregs), M2 macrophages, and immature dendritic cells) and anti-tumor (CD8+ T cells, CD4+ T cells, activated dendritic cells, and M1 macrophages) immune cells were up-regulated." (PMID 35720326, 2022). "Our results with selective depletion of CD4+ or CD8+ T cells and the generation of cancer-antigen specific immunological memory suggest that the dominant effect of VIP-R antagonists is via inhibition of paracrine signaling of VIP produced by tumor cells on T cells that express the VIP-R." (PMID 36302761, 2022). "From another study that employed BiTE to target tumor-specific antigens, the intravenous administration of CD3xPDL1 BiTE could activate CD3 positive T cells (either CD4 positive or CD8 positive) and NKT cells that specifically killed PD-L1 positive tumor cells." (PMID 35418130, 2022). "It is important to note that, in the LS cohort, following anti-CTLA4 mAb therapy, compared to the isotype control, while the frequency of tumor infiltrating inflammatory CD4+T cells was high, there was no significant increase in the inflammatory phenotype in the lung and peripheral circulation." (PMID 35741331, 2022). "Therefore, we further excluded a relative small number of factors, that is, CD4+ T-cell count of pre-NCIO (n = 39), CD4+ T-cell rate of pre-NCIO (n = 40), SUVmax of tumor post-NCIO (n = 50) and △SUVmax rate of tumor post-NCIO (n = 31), even though they had significance in univariate analyses." (PMID 36776373, 2022).
tumor (continued). "Of note, the main CD4+ and CD4− iNKT cell subsets were not equally effective in tumor control: in fact, liver-derived CD4− iNKT cells were found to be the main mediators of tumor immune surveillance in vivo, by sustaining a TH1-type CD8+ T and NK cell-mediated immune response via IFNγ production." (PMID 35615083, 2022). "As MSCs, tumor cells have the ability to promote the generation of Treg cells (CD4+CD25+Foxp3+) through mechanisms that may or may not involve cellular contact between T lymphocytes and tumor cells or MSCs." (PMID 36661506, 2022). "This resulted in the abrogation of the effects of estradiol on tumor-infiltrating Treg cells (CD4+CD25highCD127low) and the concomitant destruction of ERα and suppression of FOXP3 expression to terminate the suppressive effects of Tregs on both CD8+ and CD4+(CD4+CD25int) effector T cell subsets." (PMID 35563441, 2022). "We found that KRAS is substantially correlated with tumor immune cell infiltration, including B cells, CD8+T cells, CD4+T cells, macrophages, neutrophils, and dendritic cells, suggesting that KRAS may affect tumor processing and prognosis through cancer immunity." (PMID 35563733, 2022). "As both 5-FU and cisplatin chemo-immunotherapies increased activated and proliferating CD8+ and CD4+Foxp3- T cells, we depleted CD8+ or CD4+ T cells throughout the treatment schedule in AB1-HA tumor-bearing mice to test whether these cells were required for effective chemo‐immunotherapy." (PMID 35634282, 2022). "Of note, since MHC class II-mediated antigen presentation is mainly achieved by professional antigen presenting myeloid cells such as dendritic cells (DCs) and macrophages, but also B cells, CD4+ T cell-mediated immune responses do not require MHC class II expression on tumor cells." (PMID 36303101, 2022). "Furthermore, when comparing HCC tissue samples by median of nuclear STAT3 expression, CD3-, CD4-, CD8-, and FOXP3-positive immune cell counts were significantly higher in tumor tissues with high nuclear STAT3 expression compared to tumor tissues with low nuclear STAT3 expression of the tumor cells." (PMID 35267462, 2022). "In addition, Moreover, treatment with SGLT2 inhibitor promoted tumor infiltration by CD45+CD4+ and CD45+CD8+ T cells in STING normal expressed K7M2 tumors, while not in in STING silenced K7M2 tumors." (PMID 35662245, 2022). "However, even in the absence of CD8+ T cells, CD4+ T cells can directly kill tumor cells via the IFN-γ mechanism." (PMID 35935838, 2022). "Furthermore, compared to parental CAR-T, hNELFB-expressing CAR-T conferred more tumor infiltration of CD8+ and CD4+ T cells, and higher memory marker CD127 expression and fewer cells with the exhaustion markers TIM3+CD39+ in both CD8+ and CD4+ populations." (PMID 35444206, 2022). "Moreover, the stemness index was significantly correlated with immune cells participating in tumor killing, such as CD8 + T cells, macrophage M1 type, activated NK, DC, and CD4 + memory T cells, while being negatively correlated with macrophage M2 type and naïve B and CD4 + T cells." (PMID 35310908, 2022). "Investigations of immunocompetent and immunodeficient mice have shown that a responsive immune system is vital for the optimal efficacy of IRE, although a murine sarcoma model did not reveal any tumor-infiltrating CD4+ or CD8+ T lymphocytes within six hours after IRE." (PMID 35740542, 2022). "Since another team has demonstrated that this tumor-specific CD39+ CD4+ TILs population expresses CXCL13, PD-1 and TOX exhaustion makers and this population could contribute to tumor-specific CD8+ T cell proliferation and DC maturation through in situ reactivation with PD-1 blockade." (PMID 35008422, 2022). "Interestingly, increased expression of FasL was observed on PIM2−/− CD4+ and CD8+ cells, which may contribute to enhanced tumor cell killing." (PMID 36429128, 2022).